BRCA1 (BRCA1 DNA repair associated)
Diseases named in the same sentence as BRCA1 in open-access papers (continued):
Sharing a sentence is not in itself a finding about the gene and the disease.
prostate carcinoma (continued). "We conclude that the inclusion of DDR genes other than BRCA1/2 shared by both cancers considerably increases the detection rate of potentially actionable variants, which are triplicated in pancreatic and almost doubled in prostate cancer." (PMID 35563100, 2022). "Pathogenic germline mutations in BRCA1/2 are drivers of breast, ovarian, and prostate cancers." (PMID 36350633, 2022). "A differential response to olaparib treatment among men with metastatic castration-resistant prostate cancer harboring BRCA1/2 versus ATM mutations has been observed, in which patients with BRCA1/2 mutations respond to olaparib treatment but not those with ATM mutations." (PMID 36429046, 2022). "A meta-analysis reported a moderate association between BRCA1 mutation and prostate cancer." (PMID 35303741, 2022). "Moreover, TPX2 mRNA levels are increased in BRCA1/2-mutated breast and prostate cancers, and high TPX2 gene expression levels correlate with the sensitivity of cancer cells to olaparib." (PMID 36350633, 2022). "However, multiple studies have noted that patients with prostate cancer harboring BRCA2 mutations are more responsive to PARP inhibitors compared to BRCA1 mutation-positive patients." (PMID 36185208, 2022). "The GALAHAD trial enrolled 165 metastatic castration-resistant prostate cancer patients with germline pathogenic or somatic biallelic pathogenic alterations in BRCA1 or BRCA2 (BRCA cohort), or in other prespecified DDR genes (non-BRCA cohort), who were treated with niraparib 300 mg twice daily." (PMID 36010882, 2022). "For example, prostate cancer patients with BRCA1- mutations could be selected for clinical trials and for treatments with olaparib and ATM inhibitor, provided that the drug combination is approved by the FDA." (PMID 35055413, 2022). "Moreover, TPX2 mRNA levels are increased in BRCA1/2-mutated breast and prostate cancers, and high TPX2 expression levels correlate with the sensitivity of cancer cells to PARP-trapping inhibitors." (PMID 36350633, 2022). "We hypothesized this differential efficacy may be explained by distinct genomic landscapes of prostate cancer harboring BRCA1 versus BRCA2 mutation." (PMID 36185208, 2022). "The BRCA1/2 germline and/or somatic pathogenic variants (PVs) are key players in the hereditary predisposition and therapeutic response for breast, ovarian and, more recently, pancreatic and prostate cancers." (PMID 35563100, 2022). "The higher number of significant concurrently mutated genes in other molecular pathways may explain the decreased efficacy of PARP inhibitors in prostate cancer harboring BRCA1 mutations compared to those with BRCA2 mutation." (PMID 36185208, 2022). "Using the WGS data, we assessed the presence of variants and/or mutations in several genes that are known to be frequently mutated in prostate cancer (BRCA1, BRCA2, RB, PTEN, CDK12, PI3K, ADP-ribose, PIK3GA, PIK3CB and PIK3R1, AKT, CYP17, IGF 1, EGF, and BCL2)." (PMID 36643868, 2022). "BRCA1 in all types of prostate cancer was the target of pathogenic splice-disrupt variants." (PMID 35286517, 2022). "Moreover, prostate cancer with BRCA2 had better outcome as compared to those with BRCA1 mutations, after treatment with PARP inhibitors." (PMID 36010882, 2022). "If this finding is replicated by larger studies, the PRS may prove to be useful in cancer prevention and surveillance by identifying BRCA1 carriers at greater risk of developing aggressive prostate cancers." (PMID 34320204, 2022). "In a pooled analysis of 5 studies, men with BRCA1 mutated prostate cancer compared to BRCA2 mutated had a lower PSA50 response rate (23.8% vs. 65.2%), lower overall response rate (26.3% vs. 50%) and a lower median radiographic progression-free survival (4.1 months vs. 10.1 months)." (PMID 36185208, 2022). "BRCA1 splice-disrupt variants are involved in different types of prostate cancer." (PMID 35286517, 2022).
prostate carcinoma (continued). "In addition, although mutations in BRCA1/2 increase the risk of prostate cancer and pancreatic cancer, surveillance for these cancers has not been defined." (PMID 35191009, 2022). "In this study, we have screened 30 familial prostate cancer patients for BRCA1 and BRCA2 mutations." (PMID 34242281, 2021). "Early identification of germline BRCA1/2 mutations may be relevant for the management of Moroccan prostate cancer patients." (PMID 34242281, 2021). "Because BRCA1 is a prostate cancer susceptibility gene (with an estimated risk for prostate cancer of two- to four-fold by the age of 65), and the BRCA1 protein interacts with the BARD1 protein, we considered BARD1 to be a candidate prostate cancer susceptibility gene." (PMID 34771627, 2021). "Furthermore, we separated BRCA1 and BRCA2 in the subgroup analysis, and found that BRCA2 is likely the most important mutation in prostate cancer, and the impact of BRCA1 needs to be clarified in future studies." (PMID 34975480, 2021). "In fact, previous studies have identified some single-nucleotide polymorphisms associated with prostate cancer risk including c.442-34C>T (rs799923), c.1067A>G (rs1799950), c.4837A>T (rs1799966), c.4357+117G>C (rs3737559) for BRCA1 gene and c.1114A>C (rs144848) for BRCA2 gene." (PMID 34242281, 2021). "Based on previously estimated population frequencies of BRCA1 and BRCA2 mutations, it was estimated that BRCA1 mutations confer a relative risk of prostate cancer of approximately 3.7-fold and 8.6-fold, which translates to an 8.6% and 15% cumulative risk by age 65 years." (PMID 34356066, 2021). "To date, few studies have explored this possibility, although differences in response to PARPis in prostate cancer have been reported based on whether the tumour was BRCA1 or BRCA2 mutated." (PMID 34445211, 2021). "However, they later performed another meta-analysis and showed that prostate cancer incidence is increased by BRCA1 or BRCA2 mutation." (PMID 34577828, 2021). "However, olaparib-based therapies were tested mainly for breast, ovarian, pancreatic and prostate cancer cases with a mutation in high-penetrance genes BRCA1 and BRCA2." (PMID 32252452, 2020). "To determine the clinical significance, we analyzed in MH BRCA retrospectively in 149 BRCA1/2 variant positive cases from a total of 346 patients with breast, ovarian, or prostate cancer, which were sequenced at the YCH to test for an indication of HBOC or HPC syndrome, respectively." (PMID 32486089, 2020). "In addition to breast, ovarian, and pancreatic cancers, BRCA1/2 genes have been associated with prostate cancer (PC)." (PMID 33351846, 2020). "Interestingly, for ovarian and prostate cancer, BRCA1-type HRD deficiencies were more prominent in primary cancer compared to metastatic cancer." (PMID 33149131, 2020). "In addition, BRCA1 PV/LPVs have been associated with an increased risk of colon cancer, prostate cancer, and pancreatic cancer." (PMID 32046255, 2020). "In addition, BRCA1 alterations have been associated with an increased risk of colon cancer, prostate cancer and pancreatic cancer." (PMID 32365798, 2020). "Interestingly, ARAP3 was observed mutated in metastases of a prostate carcinoma carrying germline mutations in BRCA1." (PMID 31294536, 2019). "Familial clustering of prostate cancers was reported and ~5% of cases of prostate cancer could be directly related to highly penetrant mutations at the level of BRCA1, BRCA2, and HOXB13." (PMID 31366128, 2019). "The impact of BRCA1/2 mutations on the cellular immune phenotype of prostate cancer is largely unknown." (PMID 31549213, 2019). "TOPARP-A (The Trial of PARP Inhibition in Prostate Cancer) phase 2 trial studied the PARP inhibitor olaparib in mCRPC patients showing good response rates particularly for BRCA1/2 or ATM gene-mutated tumours that justified the breakthrough therapy designation by FDA (Food and Drug Administration)." (PMID 29606109, 2018).
prostate carcinoma (continued). "Furthermore, recent studies showed that nearly 20% of prostate cancer patients who carry the BRCA1 biallelic mutation are at risk for developing castrate resistant prostate cancer." (PMID 30036938, 2018). "The IMPACT study (Identification of Men with a genetic predisposition to ProstAte Cancer: Targeted screening in BRCA1/2 mutation carriers and controls) evaluated a tailored PC screening in 1522 men with BRCA1/2 germline mutation, proposing annual PSA tests and a prostate biopsy if PSA >3 ng/mL." (PMID 30234108, 2018). "BRCA1 mutation has been recently reported to promote migration and invasion by interacting with Ezrin-Radixin-Moesin proteins in the plasma membrane. β-hCG has also been demonstrated to promote metastasis in prostate cancer cells." (PMID 28869585, 2017). "Increased risk of prostate cancer (PCa) is observed in men with BRCA1/BRCA2 mutations." (PMID 28812325, 2017). "Our results suggest that risk profiling on the basis of PRSs may identify male carriers of BRCA1/2 mutations at both sufficiently reduced or increased risk of breast or prostate cancer, with implications for their clinical management." (PMID 28448241, 2017). "BRCA1/2 mutations increase the risk of breast and prostate cancer in men." (PMID 28448241, 2017). "Most BRCA mutations identified in patients with prostate cancer are somatic, and, compared with low mutation levels in early prostate cancer, ∼15% of patients with metastatic androgen therapy–resistant prostate cancer harbor functionally relevant somatic mutations or deletions in BRCA1 or BRCA2." (PMID 28487881, 2017). "Mutations in BRCA1 or BRCA2 define a subset of prostate cancer patients." (PMID 28676659, 2017). "PRSs may provide informative cancer risk stratification for male carriers of BRCA1/2 mutations that might enable these men and their physicians to make informed decisions on the type and timing of breast and prostate cancer risk management." (PMID 28448241, 2017). "The exact role of taxane based chemotherapy for the treatment of BRCA1/2 mutated prostate cancer patients has therefore to be further elucidated but our data suggest that patients with known BRCA1/2 mutation should be carefully monitored for PSA response when receiving a taxane based chemotherapy." (PMID 28676659, 2017). "Since this advancement, considerable research has investigated whether BRCA1/2 mutations bestow risk of prostate cancer." (PMID 26236408, 2015). "It is frequently hypothesised that the risk of prostate cancer associated with mutations in BRCA1/2 varies by age at diagnosis." (PMID 26236408, 2015). "Interestingly, members of the miR-15/107 group of miRNAs are known to be dysregulated in a number of neoplastic disorders, many of which, such as breast, ovarian, and prostate cancers, also demonstrate loss of BRCA1 function." (PMID 26257769, 2015). "Prior data suggests that men carrying mutations in the BRCA1& 2 genes may be at increased risk of developing prostate cancer." (PMID 25047061, 2014). "Although BRCA1/2 mutations are predominantly associated with breast and ovarian cancer risk the risk of prostate cancer is increased in males, and TL may be useful for risk stratification." (PMID 24489760, 2014). "It has been identified that common variation in BRCA1 gene is also associated with prostate cancer." (PMID 25426449, 2014). "Notably, mutations in BRCA1 have been implicated in risk of hereditary cancers, such as breast, ovarian, pancreatic, and prostate cancer, whereas reduced levels of BRCA1 mRNA and protein have also been associated with sporadic tumours." (PMID 23776525, 2013). "This is also consistent with previous report that HOXB13 acts as repressor of androgen receptor signaling in prostate cancer, which may affect BRCA1 (cofactor associated with AR)." (PMID 23630576, 2013). "In addition, the inheritance of a BRCA1 mutation has been linked with an increased risk of endometrial, pancreatic, and prostate cancer." (PMID 22312502, 2011).
prostate carcinoma (continued). "Prostate cancer risk is also higher in BRCA2 compared to BRCA1 carriers." (PMID 17213823, 2007). "BRCA1 mutations are less common in male than female breast cancer, and also affect prostate cancer." (PMID 15798766, 2005). "BRCA2 (and to some extent BRCA1) mutations may explain the findings for pancreatic and prostate cancers." (PMID 15798766, 2005). "Whether men with LP/P BRCA1/2 variants harbor more aggressive prostate cancer remains uncertain." (PMID 39838196, 2025). "Interestingly, BRCA1/2 alterations were more frequently germline (57.4%) and biallelic (89.9%) in the “classic” BRCA1/2‐associated cancers (i.e., breast, ovarian, pancreatic and prostate cancers) compared to other cancer types (37.2% and 43.6%, respectively), including small intestine cancer." (PMID 40205657, 2025). "Furthermore, mutations in BRCA1/2 are associated with poorer outcomes in men with prostate cancer." (PMID 39796774, 2025). "Considering that BRCA1/2 mutation carriers have a significantly increased risk of prostate cancer and that prostate cancer in BRCA1/2 mutation carriers is known to be more aggressive with a worse prognosis, it is crucial to emphasize the importance of prostate cancer surveillance to male carriers." (PMID 39590130, 2024). "In this case report, we present a patient with BRCA1 mutated mCRPC who developed oligo-progressive skin metastasis to the scalp, successfully managed with excision, and discuss literature data concerning skin metastases of prostate cancer and BRCA-associated cancers." (PMID 39465866, 2024). "The efficacy of PARP inhibitors as a therapeutic option in prostate cancer is achieved through a “synthetic lethality” process with a simultaneous loss of double-stranded DNA repair function by homologous recombination (HR), in which BRCA1/BRCA2 proteins play an essential role." (PMID 37240284, 2023). "In addition, among localized prostate cancers under active surveillance in the United States, prostate cancer patients with germline BRCA1/BRCA2 or ATM pathogenic variants were 1.96 times more likely to be upgraded on re-biopsy specimens than prostate cancer patients without pathogenic variants." (PMID 37174127, 2023). "Indeed, germline mutations in BRCA1/2 genes have been associated with prostate cancer risk." (PMID 34242281, 2021). "Data from ongoing clinical trials will help to address the questions on whether we can apply PARPi beyond BRCA1/2-mutated prostate cancer; whether combining PARPi with either AR signaling inhibitors or checkpoint inhibitors will work better in HRR-deficient mCRPC than HRR-intact mCRPC." (PMID 31404966, 2019). "It is less clear whether BRCA1 mutations increase prostate cancer risk." (PMID 17213823, 2007). "The proportion of aggressive prostate cancer in BRCA1 carriers was the same as in BRCA2 carriers (86.7%), which was higher than in noncarriers (61.1%) (odds ratio [OR] = 4.87; 95% confidence interval [CI] = 1.05 to 22.60; P = .043)." (PMID 41423785, 2026). "Among prostate cancer patients carrying BRCA1/2 gPVs, all individuals with high-grade or metastatic disease carried BRCA2 gPVs." (PMID 41970070, 2026). "Poly(ADP-ribose) polymerase inhibitors (PARPi) have reshaped therapy for advanced prostate cancer, yet durable benefit remains concentrated in BRCA1/2-altered tumors, especially BRCA2, and most responders eventually relapse." (PMID 41972679, 2026). "Because the aggressiveness of prostate cancer leads to high mortality, clinical management of BRCA1 carriers should be carefully considered, and larger studies are required." (PMID 41423785, 2026). "Mutations in BRCA1/2, a crucial component of the HRR pathway, are increasingly recognized as biomarkers of aggressive disease and treatment responsiveness in prostate cancer." (PMID 41472903, 2026).
prostate carcinoma (continued). "Pathogenic mutations in BRCA1 and BRCA2 genes are thus predictive biomarkers for PARPi sensitivity in breast, ovarian, pancreatic, and prostate cancers, and are approved as companion test for PARPi indications." (PMID 39985088, 2025). "In line with previous research, we demonstrated that both men with LP/P BRCA1 and BRCA2 variants are at a high risk of prostate cancer diagnosis, with the highest risk among men carrying LP/P variants in BRCA2." (PMID 39838196, 2025). "This study therefore aimed to evaluate BRCA1/2 CNVs in advanced prostate cancer patients using droplet digital PCR (ddPCR) and compare the results with MLPA." (PMID 40725150, 2025). "We detected prostate cancer ISUP 2 or higher diagnosis in 8% and 47% of men with LP/P BRCA1 and BRCA2 variants, respectively, compared to the IMPACT study showing ISUP 2 or higher diagnosis in 45% and 63% of men with BRCA1 and BRCA2 variants, respectively." (PMID 39838196, 2025). "This study aims to demonstrate ddPCR as an alternative approach for detecting BRCA1/2 CNVs in a highly heterogenous tissue sample from advanced prostate cancer patients." (PMID 40725150, 2025). "BRCA1 promoter methylation measured by MSP was positively associated with the advanced stage of disease and Gleason scores in prostate cancer." (PMID 40075848, 2025). "breast cancer gene 1 (BRCA1) and breast cancer gene 2 (BRCA2) are key genes in HR, and their mutations are associated with aggressive prostate cancer (PCa)." (PMID 41236806, 2025). "Germline mutations, such as those in BRCA1, BRCA2, and HOXB13 genes, can confer an increased risk of prostate cancer." (PMID 40432836, 2025). "Clinically, only prostate cancer currently assesses HRR gene alterations beyond BRCA1/2 for guiding PARP inhibitor treatment." (PMID 40420266, 2025). "Ultimately, while our results highlight the potential of ddPCR for BRCA1/2 CNV detection in advanced prostate cancer, further validation is critical before its routine clinical implementation can be recommended." (PMID 40725150, 2025). "Our study of men with LP/P BRCA1/2 variants, followed by a yearly PSA screening program, indicated a higher than expected number of men with prostate cancer in the early stages at a young age but also observed poor oncological outcomes." (PMID 39838196, 2025). "The PROfound study, which evaluated the efficacy of comprehensive gene profiling (CGP) in detecting BRCA1/2 somatic mutations, highlighted technical challenges to successfully implementing CGP in diagnostic routine practice for prostate cancer patients." (PMID 40427202, 2025). "Our study demonstrates that ddPCR provides more reliable and sensitive detection of BRCA1/2 CNVs in advanced prostate cancer tissues compared to MLPA, especially in heterogeneous samples." (PMID 40725150, 2025). "In the case of acquired resistance, reversion mutations in BRCA1 or BRCA2 that restore HR proficiency are found in 50% or more of patients, including prostate cancer." (PMID 40460119, 2025). "In BRCA1/2-mutant breast, ovarian, and prostate cancers, PARP blockade combined with anti-PD-1/PD-L1 antibodies—such as durvalumab and pembrolizumab—has shown improved response rates and prolonged progression-free survival compared to monotherapy." (PMID 41373427, 2025). "For example, breast cancer susceptibility gene 1 (BRCA1) and breast cancer susceptibility gene 2 (BRCA2) have been shown to be closely associated with prostate cancer aggressiveness and patient prognosis." (PMID 39917165, 2025). "This cohort study assesses the use of poly(adenosine diphosphate-ribose) polymerase (PARP) inhibitors in patients with metastatic castration–resistant prostate cancer harboring BRCA1/2 alterations." (PMID 41037269, 2025). "Recent studies have also demonstrated that a substantial proportion of pancreatic and prostate cancer patients harbor mutations in key HRR genes, notably BRCA1/2, ATM, PALB2, and CDK12." (PMID 40830526, 2025).